RNF7 (ring finger protein 7)
Diseases named in the same sentence as RNF7 in open-access papers (continued):
Sharing a sentence is not in itself a finding about the gene and the disease.
cancer (11 papers, 2016 to 2025). A tumor composed of atypical neoplastic, often pleomorphic cells that invade other tissues. "It has been reported that RNF7 acts as an oncogenic cooperator to promote numerous cancers, and the high-expression level of RNF7 is associated with poor prognosis of cancer patients." (PMID 36644576, 2023). "The subsequent high translation of RNF7 results in the efficient degradation of the cell cycle inhibitor p27 and malignant tumor cell growth." (PMID 40251202, 2025). "Our study reveals that YTHDF1 boosts the translation efficiency of E3 ligase RNF7, which in turn accelerates the degradation of the cell cycle inhibitor p27, promoting malignant tumor cell growth in vitro and in vivo." (PMID 40251202, 2025). "According to the functional enrichment results, similar genes of RNF7 in GEPIA (Gene Expression Profiling Interactive Analysis) (cancer-pku.cn) database were enriched in the GO enrichment analysis." (PMID 36644576, 2023). "RNF7 is generally overexpressed in human skeletal muscles, heart, testis, and other many human cancers." (PMID 36644576, 2023). "How RNF7 modulates the response of ccRCC cells to sunitinib and other cancer drugs also need to be elucidated." (PMID 35562668, 2022). "Future investigations on these potential mechanisms are crucial to gain insight into how RNF7 regulates the sensitivity of cancer cells to treatments." (PMID 35562668, 2022). "The identification of a regulatory pathway from RNF7 to SOCS1/JAK/STAT3 is particularly exciting because STAT3 activation is widely observed in several human cancers." (PMID 35562668, 2022). "High expression of RING finger protein 7 (RNF7) in cancer cells is known to play a key role in tumor progression." (PMID 28252001, 2017). "RNF7 has been reported to play critical roles in various cancers." (PMID 36578229, 2023). "For instance, it was reported that RNF7 is overexpressed in prostate and lung cancers." (PMID 35562668, 2022). "Given the reported roles of STAT3 in cancers, in which RNF7 overexpression has also been observed, it will be interesting to examine whether the regulation of SOCS1/JAK/STAT3 by RNF7 also operates in other cancer types." (PMID 35562668, 2022). "Accumulating evidence also indicates that RNF7 plays a key role in several other human cancers." (PMID 35562668, 2022). "RNF7 is highly expressed in various human cancers, such as lung, liver and stomach cancers." (PMID 28252001, 2017). "We further investigated the effect of RNF7 silencing on cancer cell invasion." (PMID 28252001, 2017). "Hence, targeting RNF7 may have broad implications in cancer therapy." (PMID 35562668, 2022). "This study revealed the important functions of the RNF7-JAK/STAT3 pathway in modulating apoptosis and glycolysis, which are utilized by cancer cells to escape multiple levels of stress imposed by the immune system and various drugs." (PMID 35562668, 2022). "We revealed for the first time that in a panel of 96 genes involved in oxidative stress, proliferation, apoptosis and cancer only three genes were changed, GRX2, RNF7, and PTGS1." (PMID 27756324, 2016). "In YTHDF1 knockdown tumor cells, only RNF7 (RING Finger protein 7), also known as SAG (Sensitive to Apoptosis Gene), a crucial subunit of the RBX/ROC RING of E3 ubiquitin ligase essential for cancer cell growth, was significantly reduced compared to control cells." (PMID 40251202, 2025). "Furthermore, by screening through the criteria of the PPI network, cancer-related pathway and TRS modeling, essential features with gene symbols of EPB41, PSMA1, FGFR3, MRAS, LEP, C7orf46, LOC285000, LBP, ZNF35, SLC30A3, LECT2, RNF7, and DYNC1I1 were identified as PRBs for COAD patients." (PMID 32528533, 2020).
tumor (9 papers, 2017 to 2025). "RNF7 was found overexpressed in several tumor types, especially in lung carcinoma, and associated with poor prognosis." (PMID 28770020, 2017). "Using the hospital cohort 2 data, chi-square test was performed, which indicated that RNF7 expression was associated with tumor size, pathological T stage, grade, and American Joint Committee on Cancer (AJCC) stage, but not with any other clinicopathological features." (PMID 35562668, 2022). "Together, these findings substantiate the role of YTHDF1 in enhancing the translational efficiency of RNF7, thereby facilitating the ubiquitin-mediated degradation of the p27 proteins, and leading to robust tumor growth." (PMID 40251202, 2025). "IHC staining of xenograft tumor tissues revealed decreased RNF7 and increased p27 levels in YTHDF1 knockdown groups compared to controls." (PMID 40251202, 2025). "Accumulating evidence indicates that RNF7 functions as an oncogene and plays a key role in transformation and tumour progression." (PMID 36578229, 2023). "It was found that RNF7 act an imperative role in tumor proliferation and radiation-resistance through inactivating NF-κB and mTOR pathway or assembling tumor suppressive proteins, including NF1, DEPTOR, procaspase-3, p21, p27, NOXA, and BIM." (PMID 36644576, 2023). "Second, RNF7 overexpression facilitated tumour cell cycle progression and cell proliferation and suppressed apoptosis." (PMID 36578229, 2023). "The results showed that the RNF7 mRNA expression level was highly associated with the Karnofsky Performance Scale (KPS) score (p = 0.026), tumour size (p = 0.0003), tumour grade (p = 0.027) and recurrence (p = 0.002)." (PMID 36578229, 2023). "Compared with NBT, RNF7 was significantly highly expressed in tumour tissues and was elevated more in HGG than in LGG." (PMID 36578229, 2023). "Animal studies also confirmed that RNF7 overexpression significantly facilitated tumour growth in vivo." (PMID 36578229, 2023). "Conversely, RNF7 knockdown suppressed tumour cell cycle progression and cell proliferation and facilitated apoptosis." (PMID 36578229, 2023). "Ki‐67 immunohistochemical staining was performed to assess the proliferative index of the tumour, which also indicated that proliferation in the RNF7 overexpression group was higher than that of the control group." (PMID 36578229, 2023). "Ki‐67 immunohistochemical staining was used to assess the proliferative index of the tumour, which also indicated that proliferation in the RNF7 knockdown group was lower than that of the control group." (PMID 36578229, 2023). "RNF7 knockdown dramatically inhibited the tumor growth and increased the apoptosis in vivo, suggesting that RNF7 has an oncogenic role." (PMID 35562668, 2022). "The immunohistochemistry staining of ccRCC tissues from tumor samples from patients in hospital cohort 2 also revealed expression of RNF7 and SOCS1." (PMID 35562668, 2022). "RNF7 overexpression inhibited apoptosis and promoted glycolysis in vitro and increased tumor growth in vivo by activating the JAK/STAT3 signaling pathway by ubiquitination of SOCS1." (PMID 35562668, 2022). "Knockdown and overexpression experiments were performed to examine the effects of RNF7 on cell viability, apoptosis, and glycolysis in vitro and on tumor growth in nude mice in vivo." (PMID 35562668, 2022). "The elevated RNF7 expression in tumor tissues of patients with RCC was correlated with poor survival." (PMID 35562668, 2022). "By analyzing the RNF7 mRNA expression data from the TCGA database, along with tumor tissues from the hospital cohort of patients with ccRCC, we found that RNF7 was upregulated in ccRCC tissues and was correlated with poor survival." (PMID 35562668, 2022). "The underlying mechanisms appear to be associated with accumulation of tumor suppressive proteins p21, p27 and NOXA, while inactivation of ERK1/2 by RNF7 knockdown." (PMID 28252001, 2017).
tumor (continued). "Although RNF7 is inducible by the transcription factor of activator protein-1 (AP-1), RNF7 inhibits tumor-promoting functionality of AP-1 by ubiquitinylation and degradation of c-Jun7." (PMID 28252001, 2017). "Our study showed that clonogenic forming ability of DU145 and PC3 in vitro, and its tumor formation ability in nude mice were significantly decreased by RNF7 interference." (PMID 28252001, 2017). "In addition, we provided evidence showing that YTHDF1 or RNF7 depletion sensitizes tumor cells to chemotherapy drug cisplatin by increasing cellular apoptosis." (PMID 40251202, 2025). "Interestingly, RNF7 promoted tumour cell proliferation by inducing G1 to S cell cycle phase transition and inhibiting apoptosis." (PMID 36578229, 2023). "The decreased Ki‐67 expression in xenograft tumours of LY294002‐treated mice also suggested that inhibition of PI3K/AKT signalling could counteract the effect of RNF7 on promoting cell proliferation." (PMID 36578229, 2023). "Animal studies also confirmed that RNF7 knockdown significantly inhibited tumour growth in vivo." (PMID 36578229, 2023). "Transwell experiment showed that RNF7 knockdown inhibited tumour cell invasion." (PMID 36578229, 2023). "Transwell experiment showed that RNF7 overexpression promoted tumour cell invasion." (PMID 36578229, 2023). "Mechanistically, overexpression of RNF7 may activate the PI3K/AKT signalling pathway to boost tumour progression." (PMID 36578229, 2023). "To further validate whether RNF7 promotes tumour growth in tumour cells by activating the PI3K/AKT pathway, we knocked down and overexpressed human RNF7 in T98G and U‐87MG cells, respectively." (PMID 36578229, 2023). "However, the specificity of RNF7 knockdown, the effects on STAT3 activity, and a triple combination therapy of sunitinib, STAT3 inhibition, and RNF7 knockdown on regulating tumor growth in vivo need to be investigated further." (PMID 35562668, 2022). "Besides, GSEA found that PI3K/AKT pathway might be related to the function of RNF7 in tumour, which was further verified by WB and rescue experiments using LY294002, a widely used PI3K/AKT inhibitor." (PMID 36578229, 2023). "Furthermore, in the early stages of tumor formation, RNF7 can negatively influence differentiation, proliferation, and cell growth through targeting c-Jun/AP-1, and in the later stage, the opposite result occurs by targeting IκBα/NF-κB based on the availability of F-box proteins." (PMID 36644576, 2023). "Among the eight genes, five genes (BRCA1, TRIM37, RNF25, CDC27, and UBE2H) were significantly upregulated and three genes (RNF7, NPEPPS, and NCCRP1) were significantly down regulated in the tumor tissues." (PMID 33414811, 2020). "Of the eight genes we identified, three genes (RNF7, NPEPPS, and NCCRP1) were down-regulated and the remaining five (BRCA1, TRIM37, RNF25, CDC27, and UBE2H) were up-regulated in tumor tissue compared to normal pancreatic tissue." (PMID 33414811, 2020). "Results showed that gene signatures such as PSMA1, FGFR3, C7orf46, RNF7, and ZNF35 were differentially expressed in normal and tumor samples with the P-value < 0.05." (PMID 32528533, 2020).
RNF7 also shares sentences with these, for which no sentence is quoted: breast carcinoma (3 papers); acromegaly (1); Alzheimer disease (1); Anxiety (1); autoimmune disease (1); colorectal cancer (1); dilated cardiomyopathy (1); gastric cancer (1); heart failure (1); infection (1); inflammatory bowel disease (1); liver fibrosis (1); ovarian carcinoma (1); pancreatic (1); prostate (1); rheumatoid arthritis (1); systemic lupus erythematosus (1); T-cell deficiency (1).